BDNF (brain derived neurotrophic factor)
Diseases named in the same sentence as BDNF in open-access papers (continued):
Sharing a sentence is not in itself a finding about the gene and the disease.
depression (continued). "While the BDNF level changes remain conflicting in blood, interestingly, the analysis of the DNA methylation level at BDNF Promoter IV in the whole blood revealed a significant association with anxiety and depression symptoms, but not with any motor or cognitive performances." (PMID 38256050, 2024). "Moreover, the impact of the eCB system on depression may, in part, be attributed to its influence on BDNF and, consequently, the process of neurogenesis." (PMID 38273283, 2024). "Extensive studies on BDNF lend support to the “neurotrophic hypothesis” of depression." (PMID 39355088, 2024). "However, further studies are needed to investigate the relationships among SYT4, BDNF, and sex hormones in female patients with depression to develop optimized precision interventions for treating depression, especially for females, who have a greater lifetime incidence of depression than males." (PMID 38297157, 2024). "The neurotrophic hypothesis makes the BDNF an important biomarker of depression." (PMID 38337722, 2024). "The relationship between GDNF and depression suggests that it might act in parallel to BDNF." (PMID 38519465, 2024). "In addition, it has been demonstrated that tPBM (810 nm) significantly increases the BDNF level in the hippocampus of mice with brain trauma, depression, and ischemic stroke, which may be beneficial to neurogenesis and synaptogenesis." (PMID 38317779, 2024). "We then tested whether activation of residual BDNF could reverse depression‐like symptoms." (PMID 38155473, 2024). "Importantly, injecting the exogenous BDNF into hippocampus can ameliorate the depression symptoms." (PMID 38421829, 2024). "The chemical hypothesis of depression suggests that the antidepressant effect of relevant drugs is related to the increased expression of neurotrophic factors such as BDNF; in this context, estrogens have been shown to upregulate BDNF in the rat hippocampus." (PMID 39081530, 2024). "Hence, not only may the downregulation of BDNF be typical for depression, but the upregulation of its precursor could also be considered a biomarker of the depression state." (PMID 38542252, 2024). "Therefore, when treating depression, restoring the balance between pro‐BDNF and mBDNF by inhibiting pro‐BDNF or supplementing mBDNF could be more effective than simply upregulating the BDNF gene." (PMID 39648800, 2024). "Therefore, we hypothesized that the potential mechanism of miR-182-5p involved in regulating depression might be mediated by targeting the expression level of BDNF, NF-α1, or nerve growth factor." (PMID 38038373, 2024). "Therefore, the treatment of depression may involve regulating the balance of intestinal microbiota, modulating BDNF-related pathways, and promoting both BDNF secretion levels and gene expression." (PMID 38389919, 2024). "Increased BDNF levels could alleviate depression and anxiety." (PMID 39000303, 2024). "The authors concluded by reverse reasoning that higher serum BDNF levels could reflect brain BDNF levels, which are known to have a beneficial effect on cerebral plasticity, and thus provide protection against the onset of post-stroke depression." (PMID 39568824, 2024). "Therefore, the effect of VDD on the occurrence of depression or the improvement of depressive symptoms by vitamin D may also occur through the BDNF signaling pathway." (PMID 39135986, 2024). "As occurs in depression, BDNF levels may be involved in anxiety." (PMID 39408702, 2024). "Studies on the neurotrophic factor hypothesis of depression indicate that the tissue‐type plasminogen activator (tPA) plasminogen system plays an important role in the pathophysiological process of depression by regulating the transformation of pro‐BDNF to mBDNF." (PMID 39639753, 2024). "Notably, BDNF promoter methylation might be a biomarker for depression as high BDNF methylation links to the incidence of depression and severe depressive symptoms." (PMID 38818577, 2024).
depression (continued). "Therefore, more gender-specific studies are needed to verify whether the BDNF serum level might be applicable as a biomarker of depression in adolescence." (PMID 38542252, 2024). "Overall, alterations in the levels of α2-AR and BDNF are closely associated with mood dysregulation, including PPD, with dexmedetomidine showing promise in the regulation of pathophysiological changes in depression as well as possible treatment efficacy in PPD." (PMID 38270949, 2024). "However, the existence of an association between depression and low circulating levels of BDNF does not necessarily imply that the cause of the reduction in circulating BDNF is a reduction in brain levels." (PMID 39568824, 2024). "In addition to BDNF-levels, reduced glucocorticoid level after exercise may also decrease symptoms related to depression." (PMID 39670994, 2024). "Furthermore, JWX swiftly enhanced neuroplasticity signaling and proteins such as mTOR, CaMKII, ERK, and BDNF in the hippocampus while also improving BDNF expression in the hippocampal dentate gyrus in mice models of depression induced by corticosterone exposure." (PMID 38675471, 2024). "Depression, the most concerning sequela, is known to be triggered by several mechanisms, including alterations in the monoamine levels, decreased brain-derived neurotrophic factor (BDNF) levels, neuroinflammation, redox imbalance, and alteration in the hypothalamic-pituitary-adrenal axis." (PMID 38707461, 2024). "Thus, optimal temporal dynamics in the complex interactions of GCs and BDNF might be important for brain homeostasis (for example determining the contextual efficacy of BDNF stimulation), and dysrhythmicity may contribute to the pathophysiology of depression." (PMID 38645426, 2024). "Additionally, low BDNF expression is correlated with depression severity." (PMID 37953501, 2024). "BDNF is a plasticity facilitator, and the result of its deficiency can be detrimental or beneficial in some cases like depression recovery which appeared in absence of depression in both FST and SPT in CUMS group, is in agreement with Karatsoreos and McEwen." (PMID 38584231, 2024). "Dysregulation of NTFs, particularly brain-derived neurotrophic factor (BDNF), ciliary neurotrophic factor (CNTF), glial cell line-derived neurotrophic factor (GDNF), and nerve growth factor (NGF), has been implicated in various cerebral disorders, including epilepsy and depression." (PMID 39474368, 2024). "Therefore, it shows great potential in the treatment of depression as it increases BDNF levels." (PMID 38812493, 2024). "Furthermore, BDNF is implicated in the pathogenesis of diverse neurological diseases including Parkinson’s disease (PD), Alzheimer’s disease (AD), multiple sclerosis (MS), amyotrophic lateral sclerosis (ALS) and depression." (PMID 38006577, 2024). "The neurotrophic hypothesis of depression and anti-depression action is backed by evidence of decreased BDNF concentrations in mood disorders, with chronic treatment of depression leading to increased BDNF expression." (PMID 39881804, 2024). "Furthermore, in addition to the interleukin family and tumor necrosis factor, rats in an IFN-α induced depression model displayed heightened central and peripheral inflammatory markers, diminished brain-derived neurotrophic factor, and compromised learning capability." (PMID 39911552, 2024). "However, we next addressed whether activation of the BDNF/TrkB or NGF/TrkA signaling axis leads to the phosphorylation of Tau or Akt kinases in mice because of their critical role in depression like-behavior and memory decline." (PMID 39574138, 2024). "However, pro‐BDNF, which acts on p75NTR, is augmented in depression." (PMID 37953501, 2024). "Thus, serum level of BDNF could be a useful marker for the detection of the development of depression in PD patients." (PMID 38752280, 2024).
depression (continued). "According to the neurotrophic hypothesis of depression, in which neurotrophic factors play a critical but not unique role in the pathogenesis of MDD, central and serum BDNF have been associated both with the presence of this diagnosis and the effects of certain antidepressant treatments." (PMID 39408702, 2024). "The neurotrophic hypothesis of depression suggests that reduced BDNF levels in key brain regions, such as the hippocampus and prefrontal cortex, contribute to the neuronal atrophy and synaptic dysfunction observed in MDD, which in turn leads to the manifestation of depressive symptoms." (PMID 39684808, 2024). "BDNF, a critical neurotrophic factor, is essential for neuronal survival, regeneration, synaptic plasticity, and cognitive functions, all of which may be compromised in depressive disorders." (PMID 39654620, 2024). "However, the changes in the role of BDNF in depression are still elusive." (PMID 37626579, 2023). "However, A. muciniphila increases the expression of BDNF mRNA in the hippocampus, indicating its potential to enhance synaptic signaling pathways, promote neuronal connectivity, and improve the condition of patients with depression." (PMID 37492530, 2023). "As a consequence of the reduction of BDNF, impairments in synaptic plasticity would, in turn, further interfere with glutamate transmission, and this vicious cycle may be involved in the development of depression-like behavior." (PMID 37989582, 2023). "Mechanisms such as ketamine’s impact on AMPA receptors, its influence on BDNF and Trkβ signaling pathways, as well as the enhancing effect of psychedelics on neuroplasticity through the 5-HT2AR, all contribute to synaptic changes associated with depression and antidepressant effects." (PMID 37882914, 2023). "In addition, BDNF participates in the pathophysiological mechanism of depression." (PMID 36901407, 2023). "Therefore, MAPK- and GSK-3-related pathways may mediate the effects of BDNF activity in PD depression, and their role should be further investigated." (PMID 37374342, 2023). "During depression pathogenesis, synaptic transmission is often impaired; thus, brain-derived neurotrophic factor (BDNF), which plays an important role in adult neurogenesis, neuronal maturation and synaptic plasticity, has been extensively recognized as a target to resist depression." (PMID 37914710, 2023). "In humans and rodents, decreasing hippocampal BDNF concentrations may be involved in the onset of depression and anxiety, with implications regarding the hippocampus, which is considered to be involved in learning, mood, and anxiety, as a port of the limbic system." (PMID 37240050, 2023). "Since significant reductions in serum BDNF levels were verified in both MDD animal models and patients, it has been defined as a potential biomarker for depression assessment in some studies." (PMID 38012702, 2023). "Finally, BDNF, depression, and CVD could be studied together with inflammatory parameters related to depressive symptoms." (PMID 37895349, 2023). "BDNF may be regarded as a crucial biomarker of major depressive disorder (MDD)." (PMID 37432243, 2023). "Furthermore, if BDNF has been assayed for purposes of research on depression and anti-depressants, then a test could be readily available to evaluate non-astronaut applicants for spaceflight." (PMID 39484176, 2023). "Finally, the HDCA5 gene is also involved in the ketamine-induced transcriptional regulation of the brain derived neurotrophic factor (BDNF), and its phosphorylation regulates the therapeutic actions of ketamine—a therapeutic agent for the treatment of depression and anxiety." (PMID 37146008, 2023). "Thus, in the presence of concomitant CVD and depression at the time of ACS diagnosis, the role of low BDNF levels remains unclear; therefore, we cannot assess whether these lower levels represent a state of depression or a marker of it." (PMID 37895349, 2023).
depression (continued). "For example, DNA methylation might be a potential link between environmental factors and the occurrence of depression; a review showed that BDNF and NR3C1 gene methylation levels were associated with depression, but the relationship between SLC6A4 and depression was found to be contradictory." (PMID 37181891, 2023). "There is some evidence that antidepressants may modify BDNF promoter 1 methylation in depression." (PMID 36737401, 2023). "Besides, ketone bodies converted after incomplete oxidation of butyric acid excite the brain, promote neuronal growth, release brain-derived neurotrophic factor, and inhibit histone deacetylase regulatory genes, which are employed clinically to improve stroke, prevent dementia, and treat depression." (PMID 37882579, 2023). "Moreover, the authors of this study did not consider the neuropsychiatric complication of diabetes such as depression as a probable moderator of BDNF levels while recent evidence suggest that these complications might alter serum BDNF levels." (PMID 36787304, 2023). "Indeed, some studies confirm that BDNF is significantly lower in children with depression." (PMID 34590201, 2023). "Therefore, BDNF levels might be potential biomarkers for the prediction or monitoring of depression." (PMID 37089920, 2023). "Moreover, low BDNF levels are reported in patients with cognitive deficits often associated with depression and anxiety, and subjects with BDNF Val66Met polymorphism (rs6265), which affects proBDNF processing in mature forms, shows poorer visual memory, and a high risk of developing mood disorders." (PMID 37175781, 2023). "Given the association between the increase in plasma BDNF levels with the beneficial effects of BLT, which was previously reported across several other TRD treatments, BDNF-related parameters may be candidates for markers of treatment response in difficult-to-treat patients with depression." (PMID 37759825, 2023). "Additionally, in a rodent model of depression, it could boost brain-derived neurotrophic factor protein levels in the hippocampus." (PMID 37397480, 2023). "Interestingly, the BDNF levels correlated with depression score changes as well." (PMID 36787304, 2023). "Major depressive disorder (MDD) is associated with accelerated cellular aging caused by the complex effects of several factors, such as the hypothalamic–pituitary–adrenal axis, brain-derived neurotrophic factor, mitochondrial DNA, telomerase, and inflammatory stress." (PMID 36805537, 2023). "In addition, homeostatic plasticity of BDNF in the hippocampus may be related to the mechanism of acupuncture in the treatment of depression." (PMID 37780709, 2023). "Drug-naïve pediatric patients with attention deficit - hyperactivity disorder (ADHD), children with autism spectrum disorder (ASD), and adolescents with major depression (MDD) have demonstrated increased concentrations of BDNF than healthy controls." (PMID 37548699, 2023). "In rats, it was also demonstrated that omega-3 fatty acids could restore the balance of oxidative stress, the inflammatory response, the production of BDNF, and the metabolism of serotonin to prevent the nicotine withdrawal-induced escalation of anxiety and depression." (PMID 37631295, 2023). "Therefore, A. muciniphila and Amuc_1100 may alleviate antibiosis-induced anxiety and depression by regulating the BDNF/TrkB signaling pathway, or by increasing 5-HT levels in the serum and hippocampus." (PMID 37492530, 2023). "Similarly, prior clinical studies report that serum BDNF levels are reduced in people with depression but increase with antidepressant treatment, and such increase is associated with not only mood and cognitive improvement but also modulation of the overactive default mode network in the brain." (PMID 38298930, 2023).
depression (continued). "Additionally, overexpression of miR-10a downregulates the expression of Brain-derived neurotrophic factor (BDNF) in neurons and low expression levels of BDNF are hypothesized to play an important role in the pathogenesis of major depression disorder (MDD)." (PMID 37193801, 2023). "However, the factors influencing anxiety and depression among maintenance hemodialysis patients and their correlation with serum BDNF, NT-3, and 5-HT levels remain unknown." (PMID 37750080, 2023). "Additionally, evidence indicates that miR-182 is a potential regulatory microRNA for BDNF, suggesting that serum BDNF and related miRNAs could serve as valuable biomarkers for diagnosing depression or as potential therapeutic targets." (PMID 37631295, 2023). "For example, brain-derived neurotrophic factor (BDNF) has drawn particular attention in the literature for its wide-ranging effects on the central nervous system, including significant associations with schizophrenia, depression and anxiety, mood disorders, bipolar disorder, and cognition." (PMID 37761888, 2023). "Therefore, substances that upregulate peripheral BDNF level may be used to prevent and treat depression." (PMID 38082356, 2023). "Therefore, stimulation of the BDNF signaling pathway and hippocampal neurogenesis could provide a novel approach to the treatment of depression." (PMID 37603290, 2023). "Regarding BDNF, several evidence found an abnormal decrease in its serum levels in MDD patients, thereby representing a biomarker of the pathogenesis of depression." (PMID 37298063, 2023). "The exact mechanisms by which the gut microbiota causes or alters depression are not fully understood, although current evidence demonstrates that the gut microbiota can affect the development of depression, mainly through the HPA axis, and inflammation, and modify the level of BDNF." (PMID 37139495, 2023). "In addition, EA may improve chronic neuropathic pain and depression‐like behaviors by modulating the CREB‐5‐hydroxytryptamine (5‐HT)/BDNF signaling pathway." (PMID 37948105, 2023). "Moreover, K252a (TrkB/BDNF inhibitor) treatment could ablate the anti-depressive and anti-inflammatory activities of eFT508, suggesting the regulatory role of eIF4E in the synaptic processes via the TrkB/BDNF signaling during depression development." (PMID 37978167, 2023). "A reduction in BDNF levels has been demonstrated in neonatal blood samples of autistic subjects and in numerous animal models of autism and genetic syndromes related to autistic behaviours (e.g., Rett syndrome), but also in patients affected by schizophrenia and depression." (PMID 37108250, 2023). "Additionally, a study conducted on mice showed that Chaihu-Shugan-San (a mixture of several medicinal herbs) alleviated restraint stress-generated anxiety and depression through inducing NF-κB-involved BDNF expression via reversing the restraint stress-induced changes in gut microbiota." (PMID 37513676, 2023). "Therefore, the identification of novel antidepressant effect targets, especially those that regulate both BDNF-dependent rapid antidepressant action and serotonergic neurotransmission-mediated long-lasting antidepressant effect, is extremely significant for depression prevention and treatment." (PMID 37914710, 2023). "Additionally, both serotonin and BDNF contribute to the modulation of synaptic connections and structural changes in the brain during neuroplasticity, both being important in the context of mood disorders such as depression." (PMID 37631295, 2023). "Decreased levels of BDNF protein have been found in schizophrenia and in bipolar and major depression disorder (MDD) patients and correlated with cognitive dysfunction among individuals with late-life depression." (PMID 37895171, 2023). "In light of our findings, based on lack of agreement in studies, more studies are needed to clarify whether BDNF is associated with cortical physiology in younger and older adults with and without depression." (PMID 37391420, 2023).